ACE (angiotensin I converting enzyme)
Diseases named in the same sentence as ACE in open-access papers (continued):
Sharing a sentence is not in itself a finding about the gene and the disease.
heart failure (continued). "Similarly, the superiority of ACE-inhibitors over CCB with regards to risk of developing heart failure was also significant and based on moderate quality evidence (RR 0.82; 95% CrI 0.69 to 0.94)." (PMID 22480336, 2012). "The addition of a beta blocker reduced mortality by 34-35% and decreased heart failure hospitalization in chronic heart failure patients with underlying moderate to severe LVSD on top of standard therapy which included an ACE inhibitor and diuretic in the majority of patients." (PMID 24278681, 2012). "There is insufficient evidence whether the benefit of adding angiotensin II receptor blockers (ARBs) to angiotensin-converting enzyme (ACE) inhibitors outweighs the increased risk of adverse effects in patients with heart failure." (PMID 20376345, 2010). "Additionally, the dataset lacks information on participants' medication use (e.g., diuretics, ACE inhibitors, urate-lowering therapy), dietary patterns, and socioeconomic status, which may confound or modify observed associations with heart failure risk." (PMID 41404102, 2025). "In addition, the extensive use of ACE inhibitors, ARBs, beta blockers and statins in type 2 diabetes may modify the risk of heart failure, although the evidence regarding the latter is weak." (PMID 29850922, 2018). "Additionally, differential expression of LZ+/− MYPT1 isoforms in patients with heart failure could underlie the mortality benefit of ACE inhibitors in white compared with black patients." (PMID 27037223, 2016). "The elevated risk of falling in the elderly with heart failure may be explained by its pharmacotherapy (e.g. diuretics, ACE inhibitors, beta-blockers) and their association with falls, although these categories of pharmaceuticals did not individually predict falls in our study." (PMID 23919320, 2013). "In fact, results of a primary care-based dutch study (10.6% confirmed systolic heart failure) suggest that an objectified systolic HF diagnosis, specific care in an HF clinic or referrals to a cardiologist are all associated with the prescription of ACE inhibitors." (PMID 22363553, 2012). "In secondary MR, there is evidence of improvement in severity with treatment for heart failure and reduction in left chambers remodeling with ACE inhibitors/ARBs, sacubitril/valsartan, and SGLT2 inhibitors." (PMID 41598280, 2026). "Standard heart failure therapies, including beta-blockers, ACE inhibitors, or ARBs, sacubitril/valsartan, mineralocorticoid receptor antagonists and diuretics, should be employed as needed." (PMID 40673965, 2025). "Intervention studies targeting patients with heart failure have shown that ACE inhibitors and β-blockers improve prognosis, and their combination is important." (PMID 41134847, 2025). "The proteomic finding of a >20-fold increase in renal ACE and massively elevated intrarenal angiotensin II in a heart failure model is telling." (PMID 41300756, 2025). "Chronic suppression of ATII activity by ACE inhibition or AT1R blockade mitigates heart failure symptoms, most probably by the suppression of local RAS in the cardiac tissue." (PMID 40149735, 2025). "This includes the use of diuretics to manage fluid overload and the careful titration of heart failure medications, such as angiotensin-converting enzyme (ACE) inhibitors or beta-blockers, to optimize cardiac output and reduce myocardial workload." (PMID 41383640, 2025). "These peptides are mainly known for being ACE inhibitors, which underscores their biotechnological value as these types of inhibitors are used for the treatment of hypertension and heart failure." (PMID 40649895, 2025). "For those with LVEF <40%, particularly withprior myocardial infarction or symptomatic heart failure, the following arerecommended: Beta-blockers, ACE inhibitors or angiotensin II receptorblockers (ARBs), though increasingly replaced by ARNIs." (PMID 41356289, 2025).
heart failure (continued). "There are currently no clinical guidelines about the absolute treatment regimen for patients with TCM; however, the standard heart failure medications comprising Beta‐blockers, ACE inhibitors, and diuretics are also employed in these cases." (PMID 40051897, 2025). "Heart failure is treated with standard medication such as beta-blockers, angiotensin-converting enzyme (ACE) inhibitors, angiotensin II receptor blockers (ARBs), SGLT2 inhibitors and diuretics." (PMID 40983718, 2025). "With respect to medical heart failure treatment at hospital admission, patients with ischaemic HFrEF and prior MI were treated more often with ACE inhibitors/ARBs, beta-blockers, and mineralocorticoid receptor antagonists (MRAs) than were those without." (PMID 38717480, 2025). "Therapeutic approach to cardiac manifestations in IMD is similar to that used in common cardiac diseases; thus, heart failure is treated with angiotensin-converting enzyme (ACE) inhibitors, β-blockers, and diuretics." (PMID 40276563, 2025). "Secondly, based on the change in the angiotensin II/angiotensin I ratio, it can be assumed that effective ACE inhibition was achieved with the administered dose in children with heart failure." (PMID 41155980, 2025). "2/6 patients among those that presented an eGFR lower than 60 mL/min/1.73m2 were under treatment with ACE inhibitors or sartans and were affected by severe heart failure (both ICD carriers)." (PMID 40898253, 2025). "Previously, a simultaneous population pharmacokinetic analysis of enalapril and enalaprilat in ACE inhibitor-naïve children with heart failure from the LENA project was conducted." (PMID 41155980, 2025). "The patient has been advised to continue with pharmacologic therapy, including beta-blockers and angiotensin-converting enzyme inhibitors (ACE inhibitors), to manage heart failure and prevent any potential deterioration in cardiac function." (PMID 41010424, 2025). "There was an increase in the use of ACE inhibitors (22% to 28%), aldosterone antagonists (32% to 42%), and anticoagulants (38% to 48%) post-discharge, reflecting optimized heart failure therapy." (PMID 40507436, 2025). "In animal experiments, ELA/APJ can prevent stress overload-induced heart failure by inhibiting the expression of angiotensin-converting enzyme (ACE) and pathological angiotensin II signaling pathway." (PMID 40727092, 2025). "Currently taking heart failure medications (at least any ACE inhibitor/angiotensin receptor blockers and/or beta-blocker)." (PMID 39909533, 2025). "The Change the Management of Patients With Heart Failure (CHAMP-HF) registry showed that ACE inhibitors, ARBs, and ARNIs were titrated to the target dose in only one-quarter to one-fifth of patients, and less than 1% of patients received all three medications." (PMID 40142653, 2025). "None of the other patients received specific guideline-directed medical therapy for heart failure, such as ACE inhibitors, beta-blockers, or mineralocorticoid receptor antagonists, as recommended in the 2022 ESC cardio-oncology guidelines." (PMID 41140069, 2025). "This study focuses on the pharmacodynamics of enalaprilat in ACE inhibitor-naïve children with heart failure." (PMID 41155980, 2025). "The analyses of the angiotensin II/angiotensin I ratio indicate that effective ACE inhibition and thus the prerequisite for clinical effects were achieved in children with heart failure at the given dosage." (PMID 41155980, 2025). "Intervention studies in patients with heart failure have shown significant prognostic improvement with combined ACE inhibitor and β-blocker therapy." (PMID 41134847, 2025). "The management of heart failure in these patients follows standard guidelines for heart failure, including the use of ACE inhibitors, ARA-II, beta-blockers, and mineralocorticoid receptor antagonists." (PMID 40142714, 2025).
heart failure (continued). "Additional heart failure therapies included angiotensin receptor-neprilysin inhibitors (54.8%), ACE inhibitors (22.0%), angiotensin receptor blockers (12.9%), potassium-sparing diuretics (64.5%), and loop diuretics (67.7%)." (PMID 40872591, 2025). "The observed association between reduced GFR and elevated aldosterone and ACE suggests RAAS-related neurohumoral activation in AMI patients with heart failure." (PMID 41049335, 2025). "Studies should also explore the potential of CoQ10 as an adjunct to current heart failure therapies, particularly in combination with beta-blockers, ACE inhibitors, and SGLT2 inhibitors." (PMID 40507436, 2025). "In the subsequent Vasodilator Heart Failure Trial II (V-HeFT II), the efficacy of the H/I combination was compared with enalapril, an angiotensin-converting enzyme inhibitor (ACE inhibitor)." (PMID 40846813, 2025). "ACE inhibitors and spironolactone were used routinely as antifibrotic treatments in heart failure and to promote reverse remodeling." (PMID 40547134, 2025). "Polymorphisms in the angiotensin-converting enzyme (ACE) gene have been associated with an increased risk of myocardial remodeling and heart failure in smokers, suggesting that water pipe smokers with specific ACE genotypes may be particularly susceptible to heart failure." (PMID 40787514, 2025). "Where left ventricular dysfunction is identified, standard heart failure therapy with an angiotensin-converting enzyme (ACE) inhibitor (e.g., ramipril) and beta-blocker should be initiated in accordance with local heart failure guidance." (PMID 41393732, 2025). "Cardiac therapies have included ACE inhibitors for worsening mitral regurgitation and heart failure, digoxin and diuretics, and angiotensin II receptor antagonists pre-surgery." (PMID 41589305, 2025). "Recent studies have shown clinical improvements in children with heart failure treated with the angiotensin-converting enzyme (ACE) inhibitor enalapril." (PMID 41155980, 2025). "In many pathologies, including high blood pressure, heart failure and neurodegenerative diseases, dysregulation of the activity and/or expression of ACE has been reported." (PMID 40481263, 2025). "Conventional heart failure treatments, including angiotensin-converting enzyme (ACE) inhibitors and β-blockers, have been shown to halt or even reverse the progression to symptomatic heart failure when introduced early." (PMID 41002436, 2025). "Managing HIV-related cardiomyopathy involves a multidisciplinary approach, combining ART optimization with standard heart failure therapies, including angiotensin-converting enzyme (ACE) inhibitors, beta-blockers, and diuretics." (PMID 40787484, 2025). "Regarding heart failure medication, 94.8% of patients received betablockers, 79.3% diuretics, 73.7% ACE inhibitors, 31.6% ATII blockers, and 13.8% digitalis." (PMID 39685677, 2024). "Heart failure medication consisted of a beta blocker in 92.9% of patients, an ACE inhibitor in 70.1%, and an aldosterone antagonist in 65.1%." (PMID 38985244, 2024). "Dual ACE and NEP inhibitor therapy has shown enhanced efficacy in animal models of heart failure and cardiomyopathy, leading to the development of orally active molecules that inhibit both ACE and NEP, known as dual inhibitors." (PMID 39046229, 2024). "The patient was started on the standard therapy for cardiac insufficiency, consisting of beta blockers, antiarrhythmic therapy, Angiotensin-converting enzyme (ACE) inhibitors and levosimendan." (PMID 39518369, 2024). "Because pulmonary edema-induced cough brought on by ACE inhibitor-induced cough predominated over heart failure in many cases shortly after treatment, the reported cough rates in this research were probable low." (PMID 38463918, 2024). "Guidelines recommend the use of ACE inhibitors (ACEis) and beta-blockers (BBs) as heart failure therapy (HFT) in all patients with symptomatic heart failure and reduced ejection fraction, independent of the underlying etiology." (PMID 38673530, 2024).
heart failure (continued). "In a single study-based economic evaluation comparing ACE inhibitors to ARBs in heart failure management, uncertainty can arise from various sources, including sampling uncertainty and methodological assumptions." (PMID 39252272, 2024). "The present predictor analysis of the WCD registry revealed that patients suffering from NICM and receiving OMT for heart failure, especially ACE inhibitors and aldosterone antagonists, had a significantly lower risk of sustained VT/VF." (PMID 38985244, 2024). "The heart failure treatment administered included beta-blockers, spironolactone, angiotensin-converting enzyme (ACE) inhibitors, and SGLT2 inhibitors." (PMID 39224438, 2024). "In our case, the patient received both beta-blockers and ACE inhibitors briefly before scheduled surgery for heart rate control and afterload reduction and both are also pillars for heart failure management." (PMID 39881920, 2024). "The majority of patients were under heart failure medication with angiotensin-converting enzyme inhibitors (ACE or angiotensin-1 receptor (AT1) inhibitors (70.5 vs. 56.1%), betablockers (89.5 vs. 78%), or aldosterone-antagonist (61.9 vs. 36.6%)." (PMID 39598008, 2024). "Prompt treatment, including packed red cell transfusion, iron supplementation, and heart failure medications (diuretics, ACE inhibitors, beta blockers, and aldosterone antagonists), resulted in significant improvement in cardiac function within days." (PMID 38397308, 2024). "ACE inhibitors have consistently shown a reduction in overall mortality in clinical trials and systematic reviews involving patients with heart failure." (PMID 38985244, 2024). "Second, in our study, all participants were prescribed guideline-directed medical therapy for heart failure at baseline by a physician, were followed in a specialized clinic, and 45% were taking an ACE-inhibitor and a betablocker at the follow-up visit." (PMID 38724901, 2024). "Heart failure can be managed through pharmacological treatments, such as angiotensin-converting enzyme (ACE) inhibitors, beta adrenoceptor antagonists and diuretics." (PMID 39385160, 2024). "In the PARADIGM-HF trial, sacubitril/valsartan was superior to the angiotensin converting enzyme (ACE)-inhibitor enalapril in reducing the risks of death and heart failure hospitalization in patients with HFrEF." (PMID 39606217, 2024). "This strategic approach allowed us to explore the cost-effectiveness of ACE inhibitors and ARBs within the context of distinct heart failure phenotypes." (PMID 39252272, 2024). "During myocardialinjury, the Nrf2/angiotensin converting enzyme (ACE) signaling pathway functions as an antioxidant, delaying theprocess of cardiac failure and ventricular remodeling." (PMID 39076309, 2024). "ACE inhibitors are likely a more cost-effective option for managing heart failure than ARBs, particularly from a healthcare system perspective." (PMID 39252272, 2024). "Medical heart failure treatment included ACE inhibitors in 8/16 patients (50%), beta blockers in 1/16 patients (6%), and diuretics in 5/16 patients (31%)." (PMID 39376619, 2024). "The present study’s findings indicate that ACE inhibitors are generally more cost-effective than ARBs regarding the cost-effectiveness of ACE inhibitors compared to ARBs in the management of heart failure." (PMID 39252272, 2024). "Data from clinical studies demonstrated that ACE inhibitors improved cognitive function in patients with heart failure, possibly through an increase in cerebral blood flow." (PMID 38362882, 2024). "In other cardiovascular conditions, such as heart failure, however, the concomitant use of aspirin and ACE inhibitors is debatable." (PMID 38646234, 2024). "Since our patient developed infarction sequelae and heart failure, he was initiated on ACE inhibitors and beta blocker following guidelines." (PMID 38233813, 2024). "Heart failure therapy was initiated with β-blocker, diuretics, and angiotensin-converting enzyme (ACE) inhibitor." (PMID 39071534, 2024).
heart failure (continued). "For those with mild heart failure, ACE inhibitors emerge as the beacon of cost-effectiveness, boasting an ICER of $8000 per additional QALY gained." (PMID 39252272, 2024). "Angiotensin-converting enzyme (ACE) inhibitors and angiotensin II receptor blockers (ARBs) are widely used to manage heart failure by reducing cardiac strain and preventing disease progression." (PMID 39252272, 2024). "Both ACE inhibitors and ARBs are well-recognized for improving prognosis in patients with heart failure and myocardial infarction, demonstrating a beneficial effect in reducing cardiovascular mortality and reversing myocardial remodeling." (PMID 39301489, 2024). "Heart failure therapy included ACE inhibitors, betablockers, and mineralocorticoid receptor antagonists in the majority of patients with only one still receiving loop diuretics at one-year follow-up." (PMID 38535102, 2024). "The cost-effectiveness of ACE inhibitors versus ARBs in heart failure management is a pivotal consideration in optimizing patient care and healthcare resource allocation." (PMID 39252272, 2024). "He received optimal medical therapy for heart failure for six months including beta-blockers, ACE inhibitors, aldosterone receptor antagonists, sodium-glucose co-transporter-2 (SGLT2) inhibitors (dapagliflozin 10mg PO OD), and diuretics." (PMID 38910751, 2024). "This trial led to the establishment of the optimal dose of ACE-inhibitors in the international heart failure guidelines." (PMID 37600045, 2023). "Treatment of heart failure with a mildly reduced ejection fraction was initiated with an ACE inhibitor, a beta blocker, and a SGLT-2 inhibitor, resulting in improvements of LVEF and symptoms." (PMID 38784643, 2023). "At this 1st consultation, the treatment of heart failure was increased; including doses of diuretics, beta blockers and ACE inhibitors." (PMID 36803293, 2023). "In children with heart failure (HF), ACE inhibitors reduce the pressure in the aorta, resistance in the systemic blood vessels, and upper left and right chamber pressures but do not appreciably influence pulmonary vascular resistance." (PMID 36819391, 2023). "ARNIs have similar safety profile and better efficacy profile than ACE inhibitors/ARBs/any other forms of medications amongst heart failure patients." (PMID 36184714, 2023). "In the context of heart failure (HF), the focus is on heart function, and recommendations include the use of angiotensin-converting enzyme (ACE) inhibitors and β-blockers." (PMID 38292979, 2023). "All patients were under conventional treatment regimen for heart failure (angiotensin-converting enzyme (ACE) inhibitors, angiotensin receptor blockers (ARB), amiodarone, furosemide, anticoagulants)." (PMID 37297878, 2023). "Most heart failure patients are on guideline directed medical therapy, which includes ACE inhibitors (ACEI) and ARBs." (PMID 37662725, 2023). "Cardioprotective drugs, including beta-blockers and ACE inhibitors, were administered, and despite the maximum possible medical treatment, symptoms of heart failure of NYHA class III persisted." (PMID 37781295, 2023). "Treatment typically involves cessation of amphetamine use, management of heart failure symptoms, and aggressive medical therapy with agents such as beta-blockers and angiotensin-converting enzyme (ACE) inhibitors." (PMID 37736450, 2023). "Almost half of the patients (7 of 13, 53.8%) required heart failure therapy, including diuretics and ACE inhibitors." (PMID 37781308, 2023). "In children and adults with congestive cardiac failure due to this anomaly, medical management includes digoxin, beta-blockers, diuretics, and angiotensin converting enzyme (ACE) inhibitors to improve heart failure." (PMID 36945291, 2023). "Captopril is more frequently utilized as an ACE inhibitor because it has a free radical scavenger activity and is used as an antihypertensive and heart failure medicine." (PMID 36803524, 2023).